HDAC2 (histone deacetylase 2)
Diseases named in the same sentence as HDAC2 in open-access papers (continued):
Sharing a sentence is not in itself a finding about the gene and the disease.
asthma (continued). "In cases of COPD and severe asthma, decreased Histone deacetylase 2 (HDAC2) impairs the effectiveness of corticosteroids, which antioxidants like heparin could potentially ameliorate." (PMID 37587208, 2023). "Corticosteroids have been among the main modalities for the treatment of asthma, but possible reasons for their inefficacy in severe asthma are the failure to recruit HDAC2/SIRT1 and the presence of oxidatively/post-translationally modified HDAC2/SIRT1 in asthmatics." (PMID 37245015, 2023). "Passive smoking impairs HDAC2 function, which may contribute to corticosteroid-insensitive inflammation in children with severe asthma." (PMID 37312162, 2023). "Until now, roxithromycin, 1,25-dihydroxyvitamin D3, clarithromycin and other drugs have been proven to be beneficial to improve the activity of HDAC2 in asthma animal experiments, which may become a new choice for asthma treatment in the future." (PMID 38131042, 2023). "Several studies have suggested that a reduction in HDAC2 expression and activity may contribute to amplified inflammation in individuals with severe asthma or COPD." (PMID 37312162, 2023). "Finally, one key mechanism of steroid resistance in COPD and severe asthma patients is reducing histone deacetylase-2 (HDAC2) levels." (PMID 36139733, 2022). "The subsequent reduction in HDAC2 activity in COPD or asthma could lead to lower corticosteroid sensitivity and less inhibition of pro-inflammatory cytokines and chemokines in response to corticosteroid treatment." (PMID 35681424, 2022). "Another important point arising from this systematic review is that ICS can be ineffective in preventing AHR in smoking patients with asthma, a condition related to the presence of relative steroid resistance due to the impairment of histone deacetylase 2 (HDAC2)." (PMID 36499612, 2022). "This study aimed to assess whether CpG-ODNs protect against excessive Th17 immune responses in CS-induced asthma through HDAC2-dependent mechanisms and compared their effects with those of corticosteroids." (PMID 34016172, 2021). "To explore the mechanism by which CpG-ODNs treatment regulates the cytokine IL-17 A due to HDAC2 upregulation, we next examined the levels of RORt, which is an important biomarker of the HDAC2-mediated Th17 response in CS-induced asthma, by immunohistochemistry, ELISA and Western blotting." (PMID 34016172, 2021). "Emerging evidence has suggested that theophylline could downregulate the inflammatory response, locally and systemically, by increasing HDAC2 activity in patients with asthma." (PMID 34016172, 2021). "The anti-inflammatory effect of GRs is promoted by HDAC2, and studies have revealed that HDAC2 expression is decreased in patients with severe asthma and may be involved in the development of glucocorticoid resistance." (PMID 34760922, 2021). "Since CpG-ODNs reduce the inflammatory response, we examined whether CpG-ODNs modulate HDAC2 activity and expression, thereby enhancing the response to GCs in CS-exposure asthma mice." (PMID 34016172, 2021). "HDAC2 is markedly reduced in PBMCs and alveolar macrophages of patients with refractory asthma." (PMID 32112175, 2020). "Patients with asthma show reduced expression of HDAC2 compared to healthy controls." (PMID 31597362, 2019). "In steroid resistant asthma, microRNA-21-5p suppressed histone deacetylase-2 through PI3K." (PMID 30781615, 2019). "Additionally, a study found a small decrease in the expression of HDAC1 and HDAC2 in bronchial biopsies of asthma patients compared with healthy individuals." (PMID 34968229, 2019). "The mechanism of this result may be explained by steroid resistance (via the histone deacetylase 2 pathway or overexpression of glucocorticoid receptor β) in severe smoking asthma." (PMID 25901797, 2015). "In summary, HDAC2 gene expression and enzyme activity might be suppressed in patientswith asthma, resulting in NF-κB activation and increased BAL levels of IL-8, IL-5,IL-13, GM-CSF, and TNF-α." (PMID 25923460, 2015).
asthma (continued). "Reduced levels of histone deacetylase-2 (HDAC2) have been observed in patients with COPD and refractory asthma, and one mechanism of reduced deacetylase activity is inactivation of HDAC2 by oxidative stress, which has been demonstrated in epithelial cells, animal models, and patients with COPD." (PMID 22824096, 2012). "In a murine model of mixed granulocytic asthma, reduced HDAC2 expression on CD11c+DCs in the lung correlates with glucocorticoid resistance during treatment, and pharmacologic restoration of HDAC2 expression on CD11c+DCs reestablishes glucocorticoid sensitivity in a mouse model of asthma." (PMID 41246337, 2025). "The results of our study are consistent with previously reported data and show that HDAC2 protein activity in the asthma group was significantly lower than that in the normal group and exhibited an even greater decrease between the severe asthma group and the mild/moderate asthma group." (PMID 32112175, 2020). "Nevertheless, in the treatment of severe asthma, corticosteroids are ineffective in alleviating symptoms, probably because oxidative stress as well as subsequent DNA damage leads to decreased activity of transcriptional corepressors such as histone deacetylase-2 (HDAC-2)." (PMID 27274620, 2016). "Corticosteroids suppress inflammatory genes in asthma by inhibiting HAT activity and recruiting HDAC2 to the activated inflammatory gene complex." (PMID 37296627, 2023). "Several reports have revealed decreased HDAC2 activity in smokers and the sputum cells of patients with respiratory diseases, as well as in CS-exposed asthma mice, indicating that insufficient transcriptional corepressor levels and activity could be critical for asthma pathogenesis." (PMID 34016172, 2021). "This indicates that elevated miR-223 expression by e.g., neutrophils contributes to the insensitivity of corticosteroids in asthma and COPD patients by modulating HDAC2, which can worsen the severity of the disease." (PMID 32509795, 2020). "For example, reduced responsiveness to glucocorticoids in patients with severe asthma and COPD has been attributed to GR modifications mediated via histone deacetylase 2 (HDAC2)." (PMID 28774304, 2017). "HDAC2 expression and enzyme activity are reduced by oxidativestress in patients with COPD, severe asthma, and in smokers with asthma." (PMID 25923460, 2015). "Consistentwith previous reports that HDAC2 expression was reduced by oxidative stress in patientswith COPD and severe asthma, our results showed that HDAC2 gene expressionwas significantly lower in OVA/OVA rats than in saline controls." (PMID 25923460, 2015). "The most important mechanism that may explain the relative corticosteroid resistance in smokers with asthma and COPD is a reduction in the expression of the enzyme histone deacetylase 2 (HDAC2)." (PMID 34983467, 2022). "When GRβ expression was increased in patients with severe asthma, it interfered with GRα-mediated transactivation activities and specifically with the ability of GRα to bind GRE sites in HDAC2 promoter, thereby decreasing HDAC2 expression." (PMID 36012240, 2022). "Strikingly, patients with severe asthma are marked by low levels of both NRF2 and HDAC2 mRNA levels in peripheral blood mononuclear cells, reinforcing the interpretation that the decrease in the expression of these genes is a pivotal determinant of susceptibility to asthma exacerbations." (PMID 36139733, 2022). "Decreased expressed HDAC2 have been noted both in severe COPD and uncontrolled asthma, and abolishes the effect of glucocorticoids by keeping glucocorticoid receptor from deacetylation and unable to form a protein–protein complex that represses the NF-κB pathway." (PMID 35681424, 2022). "In asthma and COPD patients with high miR-223 levels, the reduction in HDAC2 could lead to lower corticosteroid sensitivity and less reduction of pro-inflammatory cytokines and chemokines in response to corticosteroids." (PMID 32509795, 2020).
asthma (continued). "To date, however, the mechanism by which oxidative stress induces severe asthma through the regulation of HDAC2 activity has not been well illuminated." (PMID 32112175, 2020). "Another explanation for increased expression of miR-223 target genes in asthma and COPD may be that miR-223 also targets HDAC2, which is important for corticosteroid sensitivity." (PMID 32509795, 2020). "Moreover, ROS diminish the activity of histone deacetylase-2 (HDAC-2) co-repressor, resulting in low efficacy of corticosteroids in COPD, severe asthma, and smoking asthmatics." (PMID 32570774, 2020). "Similarly, HDAC2 and HDAC3 are key regulators of the following disorders: rheumatoid arthritis, severe asthma and chronic obstructive pulmonary disease, and atherosclerosis." (PMID 30262728, 2018). "In this respect, reduced expression and activity of HDAC2, in particular, was noticed with macrophage tolerance, which was reported in several inflammatory models, such as lung macrophages, biopsies, and blood cells from patients with COPD, severe asthma, and smoking-induced asthma." (PMID 33868227, 2021). "A lack of recruitment of histone deacetylase 2 to the RNA polymerase compatible with histone deacetylase activity being reduced in peripheral blood mononuclear cells and alveolar macrophages from patients with asthma has been proposed." (PMID 25697361, 2015). "For example,HDAC2, but not other isoforms of HDAC, shows increased tyrosine nitration in macrophagesand peripheral lung in patients with COPD and asthma." (PMID 25923460, 2015).
colorectal cancer (50 papers, 2012 to 2026). A primary or metastatic malignant neoplasm that affects the colon or rectum. "In light of the high level of colorectal cancer intra-tumoral heterogeneity, one can assume that HDAC2 is frequently mutated in sub-clonal tumor cell populations." (PMID 35608750, 2023). "Gene expression levels of the epigenetic regulator histone deacetylase 2 (HDAC2) are deregulated in colorectal cancer, and this deregulation is tightly associated with immune dysfunction." (PMID 37046620, 2023). "In this study, we identified that HDAC2 expression levels are associated with liver metastasis, higher T stages and poor prognosis in colorectal cancer." (PMID 33325150, 2021). "In particular, HDAC2 overexpression has been described in ovarian cancer and has been associated with aggressive cutaneous T cell lymphoma, advanced-stage gastric, colorectal cancer, and shorter disease-free survival of prostate cancer patients." (PMID 35055045, 2022). "In addition, another research unveiled that HDAC2‐targeting shRNA caused suppression of the in vitro migration and invasion ability of colorectal cancer cells, which was concordant with our finding." (PMID 34586697, 2021). "In colorectal cancer, studies suggest that NcoA4 may contribute to carcinogenesis associated with loss of epigenetic regulation resulting from impaired histone deacetylase 2 (HDAC2) function and to metastatic progression." (PMID 22562579, 2012). "In colorectal cancer, the high expression of HDAC2 inhibits the recruitment of the BRD4-p-P65 complex mediated by H3K27ac, thereby suppressing the transcription of NLRP3 and the occurrence of pyroptosis (Bottom left)." (PMID 41513612, 2026). "Secondly, we have focused on exploring the role and potential mechanisms of the PJA2/HDAC2 axis in colorectal cancer cells, but we recognize that further investigation into its effects in other tumor types is warranted." (PMID 39928532, 2025). "Protocatechualdehyde (PCA) exerted anti-cancer activity by reducing the protein level of cyclin D1 through the regulation of HDAC2 in colorectal cancer cells." (PMID 40076435, 2025). "For example, single‐cell sequencing datasets for gastric cancer (HRA001689) reveal expression trends of the PJA2/HDAC2 axis that parallel those observed in colorectal cancer datasets (HRA000201)." (PMID 39928532, 2025). "In normal and colorectal cancer cell lines, the histone deacetylase 2 (HDAC2) gene had a narrow H3K4me3 peak after the first exon." (PMID 40141189, 2025). "The G-protein-coupled receptor 126 (GPR126) engendered increased transcription and translation of histone deacetylase 2 (HDAC2), which regulated Gli2 expression and enhanced colorectal cancer cell proliferation." (PMID 40170839, 2025). "In colorectal cancer, inhibition of HDAC2 promotes the NLRP3/GSDMD-mediated pyroptosis, thereby enhancing chemosensitivity." (PMID 41408324, 2025). "PCA exhibits an anti-proliferative effect against colorectal cancer cells by repressing the protein expression of β-catenin, HDAC2, and cyclin D1." (PMID 40076435, 2025). "In summary, our results identified NLRP3 as an integral functional target of HDAC2 and substantiated the NLRP3 pathway, in which HDAC2 governs pharmacological pyroptosis in colorectal carcinoma by modulating NLRP3 levels." (PMID 38804602, 2024). "We noted HDAC2-positive and HDAC2-negative colorectal cancer cells in 6 PDX samples (HROC24, HROC29, HROC48, HROC50, HROC53; data not shown)." (PMID 35608750, 2023). "From these data, we conclude that HDAC2 expression critically regulates the responses of colorectal cancer cells to 5-FU." (PMID 35608750, 2023). "The combination of FKBP3 and HDAC2 was related to oxaliplatin resistance in colorectal cancer via the PTEN/AKT pathway." (PMID 36675710, 2022). "In the present study, we found that HDAC2 was highly expressed in colorectal cancer compared to adjacent normal mucosa." (PMID 33325150, 2021).
colorectal cancer (continued). "Zhu and other studies have shown that HDAC2 plays an important role in the development of colorectal cancer and can be used as a potential therapeutic target." (PMID 33325150, 2021). "Mechanistically, HDAC2 promotes epithelial‐mesenchymal transition (EMT) in colorectal cancer cells by combining HDAC1 with EZH2 (a key histone methyltransferase), possibly through the modular scaffold function of a new lncRNA, ENSG00000274093.1." (PMID 33325150, 2021). "It was particularly noticed by Jeong and colleague that PCA can potently inhibit growth of colorectal cancer cells with suppression of HDAC2 and Cyclin D1 expression." (PMID 29285297, 2017). "This is particularly significant as we show that HDAC2 expression is increased in moderately differentiated human metastatic colorectal carcinomas in the liver compared with normal tissues." (PMID 27283986, 2016). "We then selected HDAC2 as a candidate biomarker, as it had previously been shown to be up-regulated in colorectal carcinoma and it is localized only in the nucleus." (PMID 23724067, 2013). "Nuclear expression of HDAC2 was observed in 81.9% of colorectal carcinoma, 62.1% colorectal adenoma and 53.1% of normal tissues, respectively." (PMID 24216997, 2013). "Using this method, we constructed SirT1 and HDAC2 KO vectors, which were used to establish SirT1 KO cells from the colorectal cancer cell line (HCT116) and HDAC2 KO cells from the colorectal cancer cell line (DLD1)." (PMID 23046873, 2012). "Inhibiting HDAC2 in a colorectal cancer cell line could act as a potential therapy because of exerting antiproliferative and antimigratory effects." (PMID 38534765, 2024). "As for HDAC2, the related studies mainly focus on colorectal cancer (CRC)." (PMID 37171044, 2023). "For instance, in glioblastoma tumorigenesis, HDAC2 knockdown has been shown to impede tumor-sphere formation and proliferation by upregulating miR-3189-mediated GLUT335.In contrast, HDAC2 functions as a metastasis suppressor in colorectal cancer by impeding EMT and the expression of H19 and MMP1436." (PMID 37495623, 2023). "Growth inhibition and apoptosis were observed in PA‐treated HCT116 and SW480 colorectal cancer cells, induced by a decrease in histone deacetylase 2 (HDAC2) expression and HDAC enzyme activity, and subsequent repression of c‐Myc and activation of the NF‐κB pathway." (PMID 37038620, 2023). "To test whether HDAC2 null cells are present in short-term colorectal cancer cell populations, we stained cultures of HROC24 cells for HDAC2." (PMID 35608750, 2023). "There is also a high expression of HDAC2 in the carcinogenesis of colorectal cancer." (PMID 33325150, 2021). "Moreover, the expression of H19 in colorectal cancer cells with low HDAC2 expression is higher than that in cells with high HDAC2 expression." (PMID 33267897, 2020). "High expression of HDAC2 has been seen in colorectal cancer at polyp stage (more than HDAC1 expression), suggesting that HDAC2 might be involved in the early events of cancer development." (PMID 26560874, 2016). "To determine if HDAC2 could potentially serve as an early biomarker of colorectal cancer, we also analyzed HDAC2 expression in the azoxymethane (AOM)-injected rat model that mimics early stages of the adenoma-carcinoma sequence of human CRC." (PMID 23724067, 2013). "Together, these results indicate that simultaneous knockdown of MYB, HDAC2, and FOXA2 can induce the reversion of colorectal cancer cells." (PMID 39661721, 2025).